RPUSD4 (RNA pseudouridine synthase D4)
Description:
Catalyzes uridine to pseudouridine isomerization (pseudouridylation) of different mitochondrial RNA substrates. Acts on position 1397 in 16S mitochondrial ribosomal RNA (16S mt-rRNA). This modification is required for the assembly of 16S mt-rRNA into a functional mitochondrial ribosome. As a component of a functional protein-RNA module, consisting of RCC1L, NGRN, RPUSD3, RPUSD4, TRUB2, FASTKD2 and 16S mt-rRNA, controls 16S mt-rRNA abundance and is required for intra-mitochondrial translation. Acts on position 39 in mitochondrial tRNA(Phe). Also catalyzes pseudouridylation of mRNAs in nucleus: acts as a regulator of pre-mRNA splicing by mediating pseudouridylation of pre-mRNAs at locations associated with alternatively spliced regions. Pseudouridylation of pre-mRNAs near splice sites directly regulates mRNA splicing and mRNA 3'-end processing.
Synonyms: FLJ14494
Tractability: PROTAC: ubiquitination databases record sites on it; its protein half-life has been measured.
Gene: Protein-coding gene on chromosome 11 (126,202,095 to 126,211,692, reverse strand). Ensembl gene ENSG00000165526.
Subcellular location: Mitochondrion matrix; Nucleus; Cytoplasm
Subcellular location (Human Protein Atlas): Mitochondria; Nucleoplasm
Pathways (Reactome):
Metabolism of RNA: Mitochondrial mRNA modification; rRNA modification in the mitochondrion
Gene Ontology:
Molecular function: mitochondrial ribosomal large subunit rRNA binding; protein binding; pseudouridine synthase activity; RNA binding; tRNA binding; rRNA pseudouridine synthase activity; tRNA pseudouridine synthase activity
Biological process: mitochondrial tRNA pseudouridine synthesis; mRNA pseudouridine synthesis; positive regulation of mitochondrial translation; rRNA pseudouridine synthesis; enzyme-directed rRNA pseudouridine synthesis; rRNA modification; mitochondrial RNA modification; pseudouridine synthesis; RNA modification
Cellular component: cytoplasm; mitochondrial matrix; mitochondrion; nucleus; ribonucleoprotein granule
Genetic constraint (gnomAD): Loss-of-function variants: 35 observed, 35.72 expected, observed/expected ratio (o/e) 0.98, 90% interval 0.75 to 1.3. The upper end of that interval is the gene's LOEUF score, 1.3, which puts it in group 5 of 6, group 1 being the genes least tolerant of losing a copy. Missense variants: 506 observed, 507.98 expected, observed/expected ratio (o/e) 1, 90% interval 0.93 to 1.07. Synonymous variants: 210 observed, 204.82 expected, observed/expected ratio (o/e) 1.03, 90% interval 0.92 to 1.15.
Homologues: Orthologues: chimpanzee RPUSD4 (99% identical), macaque RPUSD4 (93% identical), pig RPUSD4 (80% identical), dog RPUSD4 (80% identical), rabbit RPUSD4 (80% identical), rat Rpusd4 (80% identical), guinea pig RPUSD4 (79% identical), mouse Rpusd4 (79% identical), zebrafish rpusd4 (44% identical), tropical clawed frog rpusd4 (39% identical). Paralogues in human: RPUSD3 (24% identical), RPUSD2 (23% identical), RPUSD1 (17% identical).
Diseases named in the same sentence as RPUSD4 in open-access papers:
RPUSD4 is named in the same sentence as 6 diseases in open-access papers, as found by Europe PMC text mining. Sharing a sentence is not in itself a finding about the gene and the disease. The quoted sentences say what the papers report.
glioma (1 paper, 2021). A benign or malignant brain and spinal cord tumor that arises from glial cells (astrocytes, oligodendrocytes, ependymal cells). "Our findings revealed that MRM2, NSUN4, TFB1M, and TRMT2B were correlated significantly with most immunomodulators in glioma, whereas MRM1 and RPUSD4 were correlated negatively." (PMID 34566979, 2021).
Sepsis (1 paper, 2023). Sepsis is defined as life-threatening organ dysfunction caused by a dysregulated host response to infection. "For instance, genes mediating RNA Ψ modification (TRUB1, TRUB2, PUS1, RPUSD3, RPUSD4, PUS7, RPUSD2) were mainly suppressed in sepsis." (PMID 37701433, 2023).
cancer (1 paper, 2026). A tumor composed of atypical neoplastic, often pleomorphic cells that invade other tissues. "Notably, RPUSD4 expression showed significant positive correlation with CNV in 28 cancer types, and mRNA levels were typically elevated in samples with amplifications but reduced in those with deletions." (PMID 41496500, 2026).
tumor (1 paper, 2024). "In contrast, CNV deletions in the genes TRUB1 and RPUSD4 were maintained in most tumor types." (PMID 39162904, 2024). "The most affected tumor type was PRAD, in which the expression of five synthases, DKC1, PUS3, RPUSD4, PUS7, and TRUB2, had mostly negative effects on DSS." (PMID 39162904, 2024).
RPUSD4 also shares sentences with these, for which no sentence is quoted: prostate adenocarcinoma (1 paper); prostate carcinoma (1).